RN7SKP269 (RN7SK pseudogene 269)
Gene: Miscellaneous RNA gene on chromosome 1 (9,947,318 to 9,947,636, forward strand). Ensembl gene ENSG00000202415.
Homologues: Orthologues: chimpanzee 7SK (99% identical). Paralogues in human: 7SK (75% identical), RN7SKP176 (74% identical), RN7SKP245 (73% identical), RN7SKP90 (73% identical), RN7SKP180 (73% identical), RN7SKP47 (73% identical), RN7SKP184 (72% identical), RN7SKP78 (72% identical), RN7SKP9 (72% identical), RN7SKP185 (72% identical), RN7SKP71 (72% identical), RN7SKP170 (71% identical), and 284 more.